ZNF227 (zinc finger protein 227)
Description:
May be involved in transcriptional regulation.
Tractability: Antibody: the Human Protein Atlas places it where antibodies can reach. PROTAC: ubiquitination databases record sites on it.
Gene: Protein-coding gene on chromosome 19 (44,207,475 to 44,238,179, forward strand). Ensembl gene ENSG00000131115.
Subcellular location: Nucleus
Subcellular location (Human Protein Atlas): Plasma membrane
Pathways (Reactome):
Gene expression (Transcription): Generic Transcription Pathway
Gene Ontology:
Molecular function: protein binding; transcription cis-regulatory region binding
Biological process: regulation of transcription by RNA polymerase II; regulation of DNA-templated transcription
Cellular component: nucleus; nucleoplasm
Genetic constraint (gnomAD): Loss-of-function variants: 8 observed, 12.46 expected, observed/expected ratio (o/e) 0.64, 90% interval 0.38 to 1.16. The upper end of that interval is the gene's LOEUF score, 1.16, which puts it in group 5 of 6, group 1 being the genes least tolerant of losing a copy. Missense variants: 871 observed, 999.77 expected, observed/expected ratio (o/e) 0.87, 90% interval 0.82 to 0.92. Synonymous variants: 334 observed, 337.61 expected, observed/expected ratio (o/e) 0.99, 90% interval 0.9 to 1.08.
Homologues: Orthologues: chimpanzee ZNF227 (99% identical), macaque ZNF227 (97% identical), dog ZNF227 (86% identical), pig ZNF227 (79% identical). Paralogues in human: ZNF235 (46% identical), ZNF226 (39% identical), ZNF112 (39% identical), ZNF726 (38% identical), ZNF224 (38% identical), ZNF728 (38% identical), ZNF234 (37% identical), ZNF254 (37% identical), ZNF229 (37% identical), ZNF658 (36% identical), ZNF708 (36% identical), ZNF429 (36% identical), and 164 more.